APLN (apelin)
Diseases named in the same sentence as APLN in open-access papers (continued):
Sharing a sentence is not in itself a finding about the gene and the disease.
Obesity (continued). "In conditions combining obesity and cardiac I/R injury, apelin-13 administration to mice decreased myocardial expression of pro-apoptotic B-cell lymphoma 2 (Bcl-2)-associated X protein and increased the expression of anti-apoptotic Bcl-2, leading to reduced myocardial apoptosis." (PMID 29875677, 2018). "Expression of apelin/APJ in obesity, diabetes mellitus, and diabetes-related diseases." (PMID 29875677, 2018). "Interestingly, inhibition of apoptotic signaling was associated with reduced myocardial markers of oxidative stress suggesting that apelin activates survival pathways conditions combining cardiac I/R injury and obesity." (PMID 26542760, 2015). "Moreover, different studies in both animals and humans have shown that plasma apelin concentrations are usually increased during obesity and type 2 diabetes." (PMID 25914650, 2015). "Taken together, these results unravel a novel function of apelin in the regulation of FoxO3 nucleocytoplasmic trafficking and may provide new insights into the mechanistic basis of obesity paradox." (PMID 26542760, 2015). "This mini-review will discuss the recent advances concerning the role of apelin on energy metabolism particularly in pathophysiological situations (obesity, type 2 diabetes) and will try to establish a link between plasma apelin concentrations and metabolic diseases in humans." (PMID 25914650, 2015). "In order to evaluate whether plasma levels of apelin differ among patients with HF in relation to obesity status, patients were divided into 2 categories based on BMI: non-obese and obese patients." (PMID 26542760, 2015). "Interestingly, the resistance to obesity of Tg-apelin mice was correlated with an increase in vessel formation in skeletal muscle." (PMID 25914650, 2015). "Is obesity a main determinant of elevated plasma apelin concentration?" (PMID 25914650, 2015). "However, the role of apelin in conditions combining myocardial infarction and obesity remains to be determined." (PMID 26542760, 2015). "In addition, using in vitro and in vivo approaches, we identify apelin as a novel regulator of FoxO3 nucleocytosolic trafficking in cardiomyocytes in conditions combining myocardial injury and obesity." (PMID 26542760, 2015). "Secondly, apelin is a novel adipokine participating in obesity-related metabolic diseases." (PMID 23874984, 2013). "Based on these results, we hypothesized that an obesity-induced apelin increase in type 2 diabetes might contribute to glomerular capillary injury and diabetic nephropathy." (PMID 23577111, 2013). "Apelin was found to play an important role in obesity-related metabolic diseases." (PMID 23874984, 2013). "Apelin is an adipokine that plays a role in the regulation of glucose homeostasis and in obesity." (PMID 23227256, 2012). "It remains to establish whether the increased levels of apelin observed in obesity were an attempt to overcome either insulin resistance or obesity-related cardiovascular diseases or another metabolic defect such as apelin resistance." (PMID 23653851, 2012). "The present study demonstrates that, in obese women, the aerobic exercise associated with weight reduction and with a decrease of insulin resistance promotes a reduction of the elevated plasma apelin levels, although apelin has been viewed as a beneficial adipokine up-regulated in obesity." (PMID 23653851, 2012). "In an attempt to test our second aim reclaiming whether obesity is a cofounder for apelin serum levels association with CHC disease progression, we analyzed apelin levels in the obese (36 patients) versus lean (37 patients)." (PMID 22007137, 2011). "The roles of Omentin, vaspin, and apelin in BC, as summarised from the limited research available, highlight the need for further studies to elucidate the specific contributions of these adipokines to BC, particularly in the context of obesity’s impact on the disease." (PMID 40414892, 2025).
Obesity (continued). "In a gestational diabetes model, serum apelin levels were increased and predisposed the offspring to obesity with consequent functional damage to the testis due to the reduction in the expression of APJ receptors, signaling a possible testicular resistance to apelin." (PMID 40195898, 2025). "Moreover, emerging studies suggest that adipokines, such as resistin, apelin, and chemerin, which are overexpressed in obesity, may also possess oncogenic functions." (PMID 38255203, 2024). "Moreover, apelin demonstrates a positive correlation with indices of obesity such as BMI and WC." (PMID 39519480, 2024). "Apelin was able to further increase the expression of pro-inflammatory and proteolytic molecules induced by F. nucleatum, which may suggest that apelin may be a pathomechanistic link mediating the deleterious effects of obesity on periodontal tissues." (PMID 36902162, 2023). "Data from in vivo obesity models suggest that apelin may function as an adipokine." (PMID 36902176, 2023). "The combination of F. nucleatum and apelin resulted in the highest expression levels of pro-inflammatory and proteolytic molecules, suggesting that apelin may be a pathomechanistic link mediating deleterious effects of obesity on periodontal tissues." (PMID 36902162, 2023). "Moreover, apelin levels in insulin-resistant disorders, namely obesity, and T2DM, are increased, and apelin treatment increases insulin sensitivity, glucose tolerance, and fatty acid oxidation, representing the effectiveness of exogenous apelin on diabetes-related complications." (PMID 37424869, 2023). "In conclusion, obesity could contribute to periodontitis through apelin." (PMID 36902162, 2023). "Therefore, apelin could be a critical molecule, which may mediate the harmful effects of obesity on periodontal tissues." (PMID 36902162, 2023). "The aim of this in vitro study was to explore the regulatory effects of Fusobacterium nucleatum in the presence or absence of apelin on periodontal ligament (PDL) cells in order to test the hypothesis that apelin might be one of the pathomechanistic links between periodontal disease and obesity." (PMID 36902162, 2023). "In addition, intervention using amidation-modified Apelin-13 also diminishes the activity of 3T3-L1 preadipocytes and enhances cell apoptosis, indicating that amidation-modified Apelin-13 might alleviate obesity by promoting adipocyte apoptosis." (PMID 38089606, 2023). "Hence the increase in apelin in obesity seems natural because autocrine apelin signaling may serve as a new therapeutic target for obesity and other metabolic disorders." (PMID 36093083, 2022). "Hence, exercise and apelin may are known as regulators of energy metabolism and be anti-obesity and anti-diabetic properties." (PMID 36093083, 2022). "Current studies have shown a difference in serum apelin level between diabetic and/or obese patients and the control group, which supports the role of apelin in diabetes and obesity development and emphasizes the use of apelin as a clinical marker in diabetes and obesity." (PMID 35355561, 2022). "In diabetes or obesity with hyperinsulinemia, increased apelin is a compensatory mechanism in which it not only inhibits pancreatic secretion but also leads to insulin sensitivity and glucose uptake into insulin-independent muscle tissue and then leads to a decrease in apelin levels." (PMID 36093083, 2022). "Hence, considering the role of apelin in preventing pregnancy complications, in the continuation of the study, we will look at the effects of apelin on markers of pregnancy obesity, gestational diabetes, pregnancy blood pressure, and pregnancy cardiac hypertrophy." (PMID 36093083, 2022). "Thus, apelin overproduction by adipose tissue may be involved in several obesity-related disturbances." (PMID 34212049, 2021). "However, the current findings among Thai children found that neither apelin concentration nor obesity phenotypes were related to the APLNR G212A polymorphism." (PMID 32998691, 2020).
Obesity (continued). "Furthermore, relationships between this polymorphism and the apelin concentration or obesity phenotypes are still not clearly understood." (PMID 32998691, 2020). "Due to an increase in the inflammatory cytokines in obesity that can accelerate the expression and secretion of apelin, it is hypothesized that any decrease in the gene expression of apelin in obese and diabetic rats treated with L‐carnitine can be related to the inflammatory effects of L‐carnitine." (PMID 33278072, 2020). "However, only one previous study has provided data on the relationship between the APLN T-1860C polymorphism and obesity in Chinese women; however, it lacked proper information on this polymorphism in children." (PMID 32998691, 2020). "Having established that the administration of apelin to lean mice, thereby mimicking the obesity situation, led to an increased TNBC growth and brain metastases formation, we next wondered whether the apelinergic system could be a realistic therapeutic target for TNBC in obese conditions." (PMID 32681609, 2020). "Although apelin is known to be up-regulated in obesity and hyperinsulinaemia states in humans and mice, apelin fat mRNA expression seems to increase only in the early period in pregnant rats, suggesting that it may not be associated with physiological IR occurring in late pregnancy." (PMID 31505789, 2019). "This indicates that obesity or high-fat feeding may not be the main cause of elevated apelin, and implies that a close relationship exists between apelin and both the secretion and action of insulin." (PMID 30157220, 2018). "Currently, it is not clear that LC improves obesity-associated cardiovascular complications through localalteration of Apelin system in myocardial tissue, or viaan endocrine adaptation that is reflected by a change inserum levels of Apelin." (PMID 29845798, 2018). "Therefore, we speculate that the altered energy expenditure observed during obesity might occur via apelin-dependent mechanisms on POMC neurons since we demonstrate that apelin activates these neurons in the arcuate nucleus." (PMID 27549402, 2016). "Data regarding apelin obtained from different animal models indicate that apelin influences glucose homeostasis and may contribute to the link between increased adipose tissue mass and obesity-related metabolic and maybe inflammatory diseases." (PMID 25918733, 2015). "Thus, apelin might also prevent development of obesity through the maintenance of vascular integrity." (PMID 25914650, 2015). "In addition, obesity and IR could act as comorbid factors affecting apelin level in patients with CHC." (PMID 22007137, 2011). "To explore the expression levels of apelin/APLNR in MASLD mice, we utilized a high-fat diet (HFD)-induced obesity mouse model, which disrupts the balance between lipid synthesis and degradation, leading to lipid accumulation and cytotoxicity in hepatocytes." (PMID 39744169, 2025). "The interplay between APLN, VSFTN, and IRSN in energy balance and metabolism, particularly in insulin resistance and obesity, is noteworthy." (PMID 39109340, 2024). "Animal studies have found that amidation-modified Apelin-13 might significantly reduce the average diameter of adipocytes, mRNA and protein expression of peroxisome proliferator-activated receptor γ (PPARγ) levels and perilipin 1 (PLIN1), thereby improving the dyslipidemia caused by obesity." (PMID 38089606, 2023). "This study aimed to investigate the modulatory effect of the adipokine apelin on the action of the periodontopathogen F. nucleatum on PDL cells to better understand the relationship between periodontitis and obesity." (PMID 36902162, 2023). "According to previous studies, obesity and T2DM by inducing insulin resistance increase apelin levels." (PMID 37424869, 2023).
Obesity (continued). "Serum levels of this neuropeptide positively correlate with insulin resistance and obesity, and inflammation (particularly by TNF-α production) and oxidative stress have been proposed as the link between apelin/APJ and insulin resistance." (PMID 36902176, 2023). "It is reported that apelin and APJ play a role in metabolic diseases, glucose metabolism, atherosclerosis, cardiovascular diseases, oxidative stress, obesity, and pregnancy." (PMID 36093083, 2022). "In addition, exercise-induced adiponectin and apelin lead to mitochondrial biogenesis, decreased inflammation, decreased muscle atrophy, increased muscle hypertrophy, increased brown fat, decreased white fat, increased thermogenesis, decreased sarcopenic obesity, and increased myogenesis." (PMID 35250869, 2022). "The apelin–APJ system is considered an emerging target with potential therapeutic properties in diabetes and obesity." (PMID 35355561, 2022). "In general, it appears that exercise and apelin can increase thermogenesis in WAT, BAT, beige, and muscle, and these processes can lead to reduced obesity and metabolic disorders." (PMID 36093083, 2022). "Apelin is an adipokine, a bioactive mediator secreted by adipocytes, thereby considering apelin-APJ signaling pathways as being promising therapeutic targets in metabolic diseases, like type 2 diabetes (T2D) and obesity." (PMID 36362314, 2022). "The role of adipokines in the relationship between obesity and RCC requires confirmatory evidence in the form of a systematic review and meta-analysis, specifically for visfatin, omentin-1, nesfatin-1 and apelin." (PMID 36553076, 2022). "In addition, it is known that insulin can upregulate apelin expression in both human and murine adipocytes, suggesting the existence of a regulating loop where hyperinsulinaemia may promote apelin secretion during obesity as a compensatory mechanism to adapt to the enhanced insulin request." (PMID 35628332, 2022). "On the other hand, apelin expression is increased in WAT and its plasma level is increased in obesity." (PMID 36093083, 2022). "As tumor apelin expression or its receptor APJ have been associated with poor survival in humans, we hypothesized that the apelinergic system could also be implicated in the adverse relation between obesity and pathological complete response (pCR) to neoadjuvant chemotherapy (NAC) in BC patients." (PMID 33972642, 2021). "Therefore, apelin may also prevent the development of obesity by maintaining vascular integrity." (PMID 33679444, 2021). "Other adipokines, such as PRGN (also known as granulin/epithelin precursor), nesfatin-1 (nesfatin), visfatin/PBEF/NAMPT, apelin, RBP-4, and PAI-1 have been described as signal molecules involved in obesity and metabolic syndrome." (PMID 33192583, 2020). "However, since exercise training upregulates muscle apelin expression in obese subjects, increasing the levels of physical activity among obese children could be an alternative and beneficial pathway to prevent obesity-related metabolic diseases." (PMID 32998691, 2020). "Therefore, the present study aimed to examine concentrations of apelin and anthropometric-cardiometabolic parameters in obese and non-obese children and to search for associations of APLN T-1860C and APLNR G212A polymorphisms with apelin levels and obesity among Thai children." (PMID 32998691, 2020). "Much data suggests intersecting activities between the adipokine apelin (APLN) and the pathologic processes of obesity and osteoarthritis (OA), with APLN modulating cartilage, synovium, bone, and various immune cell activities." (PMID 32420902, 2020). "In our work, we showed that in obese mice or in mice in which apelin was infused to attain obesity‐like levels, TNBC growth was facilitated, but also that tumour apelin expression was increased." (PMID 32681609, 2020).
Obesity (continued). "Similarly, our results confirm that the APLN T -1860C polymorphism is not linked with apelin levels, whereas the C allele of this gene polymorphism was significantly associated with increased risk of obesity by approximately four times in Thai girls, after adjusting for confounding factors." (PMID 32998691, 2020). "Therefore, our findings suggest that APLNR G212A polymorphism may not be involved in circulating apelin concentration and obesity among Thai children." (PMID 32998691, 2020). "Although molecular studies on APLN and APLNR genes have been performed, the relationships of these genes with obesity remain limited, especially in children." (PMID 32998691, 2020). "Levels of apelin and APJ mRNA increase in white adipose tissue and plasma with obesity than in control subjects." (PMID 29977292, 2018). "Thesefactors have important roles in cardiovascular dysfunctionsin animals and humans with obesity, diabetes and insulinresistance.Recent in vivo and in vitro findingshave shown that TNF-α induces Apelin gene expression inobese mice." (PMID 29845798, 2018). "The opposing effects of apelin/ACE2 and angiotensin II have been shown in health and diseases such as heart failure, atherosclerosis and obesity/diabetes." (PMID 28293165, 2017). "In contrast, higher levels of apelin and APJ mRNA have been found in pathological conditions such as obesity and diabetes." (PMID 27703805, 2016). "We next examined physiopathological features and effects of post-treatment with apelin in a mouse model combining I/R injury and HFD-induced obesity." (PMID 26542760, 2015). "We also observed that obese patients with type 2 DM had significantly higher apelin levels than non-diabetic obese subject (1.62±1.43 ng/mL vs 0.97±0.78 ng/mL, P = 0.015) confirming that increased apelin levels are directly associated with the presence of diabetes rather than obesity itself." (PMID 23227256, 2012). "Circulating serum apelin level varies in different stages of CHC, which in conjunction with IR and obesity, would contribute to fibrosis progression." (PMID 22007137, 2011). "The aim of this review was to summarize the currently available literature on the apelin-APJ system to better understand the pathomechanistic relationship between periodontitis and obesity and to determine the potential clinical relevance of apelin for diagnostics and therapy." (PMID 39189510, 2024). "Our findings indicate that 12 weeks of HIFT supplemented with spinach-derived thylakoid reduced levels of leptin, resistin, vaspin, visfatin, apelin, RBP4, chemrin, semaphorin3c and insulin resistance while increasing adiponectin and omentin levels in men with obesity." (PMID 37576981, 2023). "In obesity, apelin appears to act to inhibit adipogenesis through negative feedback at the autocrine level, as obesity increases apelin and APJ secretion." (PMID 36093083, 2022). "While the inhibition of apelin leads to obesity and obesity increases with the lack of apelin signaling." (PMID 36093083, 2022). "The apelin–APJ signaling system has emerged as an important biomarker and a novel therapeutic target against the development of metabolic diseases, especially diabetes and obesity." (PMID 35355561, 2022). "Apelin levels are increased in obese subjects as well as in subjects without severe obesity but with IGT or overt diabetes." (PMID 35628332, 2022). "It is reported that exercise-induced apelin in mothers activates sarcolipin and uncoupling protein 3 (UCP3) in the muscles of children and protects them from obesity because Sarcolipin and UCP3 regulate thermogenesis in muscles to improve metabolic homeostasis." (PMID 36093083, 2022). "Moreover, even if the use of BMI as a parameter for obesity is used in daily clinical practice, the use of waist-to-hip ratio as parameter for central obesity could be more appropriate to study the implication of obesity and apelin in response to NAC in BC patients." (PMID 33972642, 2021).